ANGEL1 (angel homolog 1)
Description:
Exhibits weak RNA 2',3'-cyclic phosphatase, catalyzing the hydrolysis of RNA molecules with a 2',3'-cyclic phosphate at the 3' end to produce RNA with a linear 3'-phosphate group. Plays a role in the non-stop mRNA decay pathway (NSD), which specifically targets and degrades mRNAs that lack a proper stop codon.
Synonyms: KIAA0759; Ccr4e
Tractability: PROTAC: ubiquitination databases record sites on it.
Gene: Protein-coding gene on chromosome 14 (76,781,733 to 76,826,246, reverse strand). Ensembl gene ENSG00000013523.
Subcellular location: Mitochondrion outer membrane; Golgi apparatus; Endoplasmic reticulum
Subcellular location (Human Protein Atlas): Nucleoplasm
Gene Ontology:
Molecular function: eukaryotic initiation factor 4E binding; protein binding; protein domain specific binding; RNA 2',3'-cyclic phosphatase activity; mRNA 3'-UTR binding; catalytic activity
Biological process: nuclear-transcribed mRNA catabolic process, non-stop decay
Cellular component: cis-Golgi network; cytosol; endoplasmic reticulum; Golgi apparatus; mitochondrial outer membrane; nucleus; perinuclear region of cytoplasm; mitochondrial matrix
Genetic constraint (gnomAD): Loss-of-function variants: 62 observed, 78.16 expected, observed/expected ratio (o/e) 0.79, 90% interval 0.65 to 0.98. The upper end of that interval is the gene's LOEUF score, 0.98, which puts it in group 4 of 6, group 1 being the genes least tolerant of losing a copy. Missense variants: 737 observed, 871.72 expected, observed/expected ratio (o/e) 0.85, 90% interval 0.8 to 0.9. Synonymous variants: 340 observed, 343.97 expected, observed/expected ratio (o/e) 0.99, 90% interval 0.9 to 1.08.
Homologues: Orthologues: chimpanzee ANGEL1 (99% identical), macaque ANGEL1 (94% identical), pig ANGEL1 (92% identical), mouse Angel1 (91% identical), dog ANGEL1 (90% identical), guinea pig ANGEL1 (90% identical), rabbit ANGEL1 (89% identical), rat Angel1 (89% identical), tropical clawed frog angel1 (41% identical), zebrafish angel1 (36% identical), Drosophila melanogaster angel (17% identical), Caenorhabditis elegans angl-1 (17% identical), and 2 more. Paralogues in human: ANGEL2 (30% identical), PDE12 (17% identical), CNOT6L (15% identical), CNOT6 (15% identical), NOCT (14% identical).
Diseases named in the same sentence as ANGEL1 in open-access papers:
ANGEL1 is named in the same sentence as 1 disease in open-access papers, as found by Europe PMC text mining. Sharing a sentence is not in itself a finding about the gene and the disease.
ANGEL1 shares sentences with these, for which no sentence is quoted: cancer (1 paper).